HMOX1 (heme oxygenase 1)
Diseases named in the same sentence as HMOX1 in open-access papers (continued):
Sharing a sentence is not in itself a finding about the gene and the disease.
ovarian carcinoma (51 papers, 2010 to 2026). A malignant neoplasm originating from the surface ovarian epithelium. "This study showed that Arvanil enhances the anti-tumor effect of cisplatin in cisplatin-resistant ovarian cancer cells, partly associated with HMOX1-related ferroptosis." (PMID 42069794, 2026). "The expression of MTF1 and BMP6 involved in iron regulation was associated with improved OS in ovarian cancer, whereas the expression of IREB2, GPI, and HMOX1 in this process was associated with poor OS in ovarian cancer." (PMID 38186569, 2023). "We quantified the heme-degrading enzyme, heme oxygenase-1 (HO-1, encoded by Hmox1) in normal peritoneum, endometriotic lesions and endometriosis-associated ovarian cancer (EAOC) of clear cell type (OCCC)." (PMID 35565370, 2022). "A growing body of evidence shows that HMOX1 is involved in chemicals‐induced ferroptosis in liver cancer, gallbladder cancer and ovarian cancer." (PMID 40495644, 2025). "Upregulation of HMOX1 promoted Fe2+ accumulation and overcame cisplatin resistance in ovarian cancer." (PMID 38767825, 2024). "HMOX1 is considered to be an oncogene in ovarian cancer and its high expression promotes proliferation in ovarian carcinoma cells." (PMID 34758842, 2021). "Similarly, co-treatment with shikonin and cisplatin has been shown to activate HMOX1 (Heme oxygenase 1) and promote iron accumulation, inducing ferroptosis and mitigating cisplatin resistance in ovarian cancer." (PMID 40630134, 2025). "Moreover, HMOX1 exhibits increased activity in cancer cells, resulting in the accumulation of tumour malignancy and the enhancement of apoptotic ability in ovarian cancer and bladder cancer." (PMID 40495644, 2025). "We propose that HMOX1 plays a pivotal role in FX-regulated ferroptosis in ovarian cancer." (PMID 40137309, 2025). "In addition, SIRT5 was found to promote cisplatin resistance (HO-1) pathway in ovarian cancer by modulating Nrf2/heme oxygenase 1 axis." (PMID 35136826, 2022). "In addition, it was certified that SIRT5 mediated cisplatin resistance in ovarian cancer by regulating the nuclear factor erythroid 2–related factor 2 (Nrf2)/heme oxygenase 1 (HO-1) pathway." (PMID 34149393, 2021). "In addition, HMOX1 overexpression has been found to be a predictor of worse prognosis in ovarian carcinoma patients." (PMID 34758842, 2021). "It was reported that inhibition of autophagy may promote EMT through the ROS/heme oxygenase-1 (HO-1) pathway in ovarian cancer." (PMID 31126310, 2019). "SIRT5 is overexpressed in ovarian cancer tissues and promotes cisplatin resistance in ovarian cancer cells by inhibiting cisplatin-induced ROS-dependent DNA damage by regulating the nuclear factor erythroid 2-related factor 2 (Nrf2)/heme oxygenase 1 (HO-1) pathway." (PMID 36505774, 2022). "Mechanistically, we show that SIRT5 contributes to cisplatin resistance in ovarian cancer by suppressing cisplatin-induced DNA damage in a reactive oxygen species (ROS)-dependent manner via regulation of the nuclear factor erythroid 2-related factor 2 (Nrf2)/heme oxygenase 1 (HO-1) pathway." (PMID 31456942, 2019). "Conversely, treatment with shikonin was shown to trigger ferroptosis by inducing heme oxygenase 1 (HMOX1) expression, thereby sensitizing ovarian cancer cells to cisplatin." (PMID 41502518, 2025). "Previous reports have shown that targeting heme oxygenase-1 (HMOX1) can induce ferroptosis in liver cancer cells and ovarian cancer." (PMID 38738174, 2024). "et Zucc.(Boraginaceae), promotes Fe2+ accumulation by upregulating heme oxygenase 1 (HMOX1), initiating ferroptosis in DDP-resistant ovarian cancer cells." (PMID 38239395, 2023). "In particular, it has been documented that GULP1 activates SMAD3 or inactivates AKT/PDK1 and MAPK in ovarian cancer cells, while it inhibits the nuclear translocation of NRF2 and subsequently reduces the expression of HMOX1 in bladder cancer cells." (PMID 34576193, 2021).
ovarian carcinoma (continued). "Early response (6 hours) of A2780 ovarian carcinoma cells to SFN treatment involves generation of mitochondrial ROS and increased transcription of NRF2 and its downstream regulated genes including heme oxygenase 1, NAD(P)H:quinine oxidoreductase 1, and KLF9." (PMID 27528021, 2016). "This suggests that TGF-β may regulate DIMP through LCN2, HMOX1, or HIF1A in ovarian cancer." (PMID 38186569, 2023). "Exploring the iron regulation in ovarian cancer, most genes integral to this process, like IREB2, HFE, BMP6, HMOX1, and ACO1, showed decreased expression compared to their normal tissue counterparts." (PMID 38186569, 2023).
cardiomyopathy (50 papers, 2013 to 2026). A disease of the heart muscle or myocardium proper. "A previous study showed that inhibiting mitochondrial lipid accumulation or lipid peroxidation had protective effect on myocardium as ferroptosis was implicated in cardiomyopathy through the Nrf2/Hmox1 axis." (PMID 35865003, 2022). "Context dependency is also indicated because Hmox1 is associated with ferroptosis in cardiomyopathy induced by doxyrubicin." (PMID 36388115, 2022). "Besides, the Nrf2/Hmox1 pathway participates in heme degradation and iron release and causes ferroptosis of the heart in doxorubicin-induced cardiomyopathy." (PMID 35280796, 2022). "Previously, we showed that ferroptosis is the major pathogenic mechanism underlying doxorubicin-induced cardiomyopathy in mice by upregulating HO-1 (Heme oxygenase-1), causing the production of excess free iron and oxidized lipids in the mitochondrial membrane." (PMID 34145214, 2021). "For example, excessive induction of HMOX1 promotes cardiac ferroptosis and leads to cardiomyopathy in mice with sickle cell disease." (PMID 39629132, 2024). "Some new keywords appeared in this period and became cores with parts of old ones, including autophagy, protect, myocardial injury, cardiomyocyte, cardiomyopathy, heme oxygenase 1, and pyroptosis." (PMID 36793476, 2023). "Ferroptosis drives cardiomyopathy induced by chemotherapy (doxorubicin) in the mouse, where upregulation of Hmox1 seems important; this ferroptotic cardiomyopathy was abolished in Nrf2-deficent mice." (PMID 36509429, 2023). "It is well known that the cardio-protective inducible enzyme heme oxygenase-1 (HO-1) plays an important role in protecting against DOX induced cardiomyopathy in mice." (PMID 37602332, 2023). "HMOX1 plays an essential role in doxorubicin (DOX)-induced ferroptosis in cardiomyopathy and has also been considered as a pro-ferroptotic gene in some other disease models." (PMID 35498043, 2022). "In some pathological states such as doxorubicin (DOX)-induced cardiomyopathy and cardiac ischemia/reperfusion (I/R), Hmox1 is significantly upregulated." (PMID 35280796, 2022). "Application of the heme scavenging protein hemopexin or Hmox1 deletion were found to reduce iron-dependent ferroptosis in this model and prevent cardiotoxicity/cardiomyopathy in SCD mice." (PMID 35326205, 2022). "Doxorubicin can upregulate heme oxygenase-1 to release free iron in cardiomyocyte, resulting in ferroptotic cardiomyopathy with HF." (PMID 35476142, 2022). "In DOX-induced cardiomyopathy, the Nrf2/Hmox1 pathway mediates heme degradation and releases free iron, resulting in ferroptosis." (PMID 35127704, 2021). "Mechanistically, treatment with DOX led to cardiomyopathy through the accumulation of nonheme iron via heme degradation in response to Nrf2-associated upregulation of HMOX1, which can be rescued by HMOX1 antagonists or in Nrf2-deficient mice." (PMID 36771298, 2023). "A study established a DOX-induced cardiomyopathy mouse model and found that heme could be rapidly degraded by upregulating heme oxygenase-1 (Hmox1), and iron was released into the bloodstream more swiftly, leading to myocardial dysfunction and ferroptosis." (PMID 37181809, 2023). "Moreover, they figured out that heme oxygenase-1 (HMOX1) was the major culprit for iron release in DOX-induced cardiotoxicity and provided intriguing insights for the first time into the role of ferroptosis in cardiac cell death linked to cardiomyopathy." (PMID 34312370, 2021). "Hmox1 can also be transcriptionally upregulated by 4-HNE to induce ferroptosis, as observed in cardiomyopathy in SCD." (PMID 39459368, 2024). "An RNA-sequencing result has shown that the expression of the heme oxygenase-1 (Hmox1) gene is significantly higher in mouse hearts treated with DOX than that of the control, which means Hmox1 is critical for DOX-induced cardiomyopathy." (PMID 35327582, 2022).
cardiomyopathy (continued). "However, this cardioprotection might be context specific or temporal, since cardiac specific Hmox1 overexpression in mice attenuates isoproterenol induced cardiomyopathy but was correlated with age related, spontaneous heart failure and chronic pressure overload." (PMID 36388115, 2022). "Administering DOX to mice induced cardiomyopathy with a rapid, systemic accumulation of nonheme iron via heme degradation by NF-E2-related factor 2 (Nrf2)-mediated up-regulation of heme oxygenase-1 (HMOX1), indicating the cardio-protective role of targeting ferroptosis for cardiomyopathy prevention." (PMID 32582710, 2020). "HMOX1 was involved in ferroptosis-mediated doxorubicin (DOX)-induced cardiomyopathy (DIC) through the accumulation of non-heme iron in response to Nrf2, which could be rescued by a HMOX1 antagonist or Nrf2-deficiency in mice." (PMID 36771298, 2023). "However, a study found that doxorubicin-induced cardiomyopathy results in the accumulation of nonheme iron via heme degradation by NRF2-mediated upregulation of heme oxygenase-1." (PMID 35082973, 2022).
glioblastoma (50 papers, 2010 to 2026). The most malignant astrocytic tumor (WHO grade IV). "HMOX1, an enzyme crucial for heme breakdown, is implicated in the progression of several cancers, including glioblastoma." (PMID 40739397, 2025). "We also investigated the role of PFKFB4 and HMOX1 in glioblastoma growth by examining death-associated genes in U87-MG cells." (PMID 40739397, 2025). "Herein, we investigated the APP-mediated alteration of HMOX1 expression and related epigenetic regulation mechanisms using glioblastoma cells harboring a Swedish mutation of APP." (PMID 27058954, 2016). "The mRNA expression levels of the PFKFB4 and HMOX1 genes were assessed in both U-87 MG glioblastoma and HDFa normal cell lines using RT-qPCR." (PMID 40739397, 2025). "This study investigated the potential of silencing the PFKFB4 and HMOX1 genes in U87-MG glioblastoma cells using small interfering RNAs (siRNAs), both alone and alongside the chemotherapeutic agents temozolomide (TMZ) and doxorubicin (DOX)." (PMID 40739397, 2025). "The analysis revealed a significant upregulation of PFKFB4 and HMOX1 expression in the glioblastoma cells compared to the normal cells." (PMID 40739397, 2025). "HMOX1, an enzyme essential for heme breakdown, is involved in the progression of several cancers, including glioblastoma." (PMID 40739397, 2025). "HSSP can specifically bind to heme oxygenase-1 (HMOX1), which is highly expressed in temozolomide-resistant glioblastoma." (PMID 38556545, 2024). "HMOX1 is highly expressed in a variety of cancers, including lung, breast, colorectal and glioblastoma." (PMID 39233332, 2024). "Interfering with this metabolism by blocking the catabolism of heme via heme oxygenase-1 (HO-1) inhibition reduced the immunosuppressive activity of BMDMs from patients with glioblastoma." (PMID 39188677, 2024). "The role of BLVR in cancer is closely related to oxidative stress: the knockdown of BLVR-A resulted in a significant increase in intracellular ROS levels in glioblastoma cells and resulted in increased HMOX-1 expression." (PMID 32082323, 2020). "An early report showed an anti-tumor effect on an orthotopic glioblastoma model U87, in combination with the Flt-1/Fc chimera, and more recent evaluation of adaphostin activity in glioblastoma cell lines identified a high level of HMOX1 induction." (PMID 20618971, 2010). "Only the T98G glioblastoma cell line was found to have elevated levels of the HMOX1 gene." (PMID 36142793, 2022). "The up-regulation of HMOX1 in solid tumor derived models, is consistent with data published for glioblastoma cell lines suggesting that these cell lines may utilize different pathways to handle the adaphostin induced oxidative stress." (PMID 20618971, 2010). "Senescence-like phenotype mediated by IFI16 in glioblastoma (GBM) suppresses ferroptosis via Heme Oxygenase-1 (HMOX1) activation, conferring radiation resistance." (PMID 40801613, 2025). "Furthermore, when we used spatial transcriptomics to identify the spatial overlap of cells that were identified to be highly connected, we saw that the HMOX1+ myeloid cells were spatially correlated with T cell exhaustion and the mesenchymal state of glioblastoma." (PMID 35177622, 2022). "In addition to glioblastoma cells, we also found Aβ-induced epigenetic regulation of HMOX1 in human T lymphocyte Jurkat cells suggesting epigenetic modification of HMOX1 in certain type of blood cells may reflect regulatory mechanisms observed in neural cells." (PMID 27058954, 2016). "Future research should investigate how knocking down HMOX1 and PFKFB4 affects drug resistance pathways in glioblastoma, such as PI3K/AKT, MAPK, and NF-κB." (PMID 40739397, 2025). "Under normoxic conditions, glioblastoma cells exhibited higher levels of PFKFB4 and HMOX1 compared to normal fibroblast cells (HDFa)." (PMID 40739397, 2025).
glioblastoma (continued). "Finally, using a human neocortical GBM model coupled with patient-derived T cells to simulate the lymphoid compartment, we validated the role of HMOX1+ myeloid cells as key drivers for the immunosuppressive microenvironment found in glioblastoma." (PMID 35177622, 2022).
kidney damage (50 papers, 2009 to 2026). "Previous studies have shown that the Nrf2/heme oxygenase-1 (HO-1) pathway regulates diabete-caused kidney damage, and that miR-505-3p aggravates oxidative stress injury through the Nrf2/HO-1 signaling pathway." (PMID 35392987, 2022). "Overexpression of sFlt-1 in HO-1 haploid deficient (Hmox1+/−) pregnant mice showed exacerbated increase in blood pressure, kidney damage, altered placental morphology and adverse fetal outcomes." (PMID 33137710, 2021). "Case reports on deficiency of HMOX1, a human gene encoding HO-1 enzyme, showed vascular injury and early atherosclerotic changes along with inflammation and nephropathy, suggesting the importance of HO-1 in vascular health." (PMID 33260980, 2020). "FPS-ZM1 boosts the activity of antioxidant enzymes, including heme oxygenase-1 (HO-1), and helps reduce kidney damage in hypertensive rats." (PMID 39796257, 2025). "Studies have demonstrated its renoprotective properties in rhabdomyolysis, where it mitigates kidney damage and ferroptosis by reducing lipid peroxidation, possibly through activation of the Heme oxygenase-1 (HO-1) enzyme." (PMID 38731887, 2024). "In addition to increasing antioxidant enzymes, empagliflozin down-regulated gene expression of nephropathy markers (Hmox1, Ngal, Tgfβ1, Mcp-1), which are also involved in inflammatory and injury processes in the kidney cortex." (PMID 34638943, 2021). "H2S-releasing aspirin, MZe786, successfully reduced blood pressure, kidney damage and improved fetal outcome in Hmox1+/− mice under high levels of sFlt-1 in part, by increasing the release of H2S as its' metabolite, TMS, is increased in MZe786 treated group and not in the aspirin group." (PMID 33137710, 2021).
lung disease (46 papers, 2004 to 2025). "Our case highlights that HMOX1 deficiency can also have marked lung disease resulting in early mortality." (PMID 33066778, 2020). "Another investigation demonstrated that acrolein induced lung diseases via elevating the expression of the Hmox1 gene." (PMID 40586291, 2025). "In response to oxidative stress and inflammatory injury, heme oxygenase-1 (HO-1) considerably influences the progression of a variety of severe diseases, such as lung disease, systemic autoimmune disease, and cancer." (PMID 31991739, 2020). "Through the analysis of 13 lung disease-modifiers genes, we found DNA methylation changes of small magnitude in two genes (HMOX1 and EDNRA)." (PMID 28289476, 2017). "Heme oxygenase-1 (HO-1) plays a crucial role in protecting against damage from inflammation and the accumulation of reactive oxygen species, particularly in severe conditions such as acute autoimmune disorders, lung diseases, and cancers." (PMID 39458978, 2024). "Moreover, the DNA methylation level at three genes (GSTM3 in NEC and HMOX1 and EDNRA in blood samples) was associated with lung disease severity." (PMID 28289476, 2017). "Polymorphisms in cytokines, their receptors, bacterial pattern recognition molecules, surfactant proteins, and heme oxygenase-1 are known to alter the course of other pulmonary diseases and should be examined as to their potential role in the development of BPD in the premature infant." (PMID 15610555, 2004). "Finally, the expression of the HMOX-1 and CXCL-8 genes may be of relevance in explaining some of the lung diseases associated to PM exposure." (PMID 37903867, 2023). "The induction of the inducible isoform HMOX1 is mostly regarded a protective measure to reduce or modulate inflammatory and apoptotic processes and has also been demonstrated to have beneficial effects in lung diseases (Constantin, Choi, Cloonan, & Ryter, 2012)." (PMID 33565273, 2021). "HMOX1 was not differentially expressed in CF patients compared with controls (Wilcoxon p = 0.11) or in patients stratified according to the lung disease severity (Kruskal-Wallis p = 0.39)." (PMID 28289476, 2017). "In addition, in NEC samples, the increase of DNA methylation at the promoter of HMOX1 was non-monotonic in CF patients stratified according to the lung disease severity." (PMID 28289476, 2017).
metabolic syndrome (46 papers, 2009 to 2026). A cluster of metabolic risk factors for CARDIOVASCULAR DISEASES and TYPE 2 DIABETES MELLITUS. "The literature suggests possible mechanisms for CO induced inflammation through feedback loops with the host enzyme heme oxygenase 1, which is elevated in the plaques and serum of psoriasis patients and associated with metabolic syndrome." (PMID 36605199, 2022). "Associations of HMOX1 (GT)n polymorphisms with components of metabolic syndrome." (PMID 25933176, 2015). "The research landscape has expanded to include endoplasmic reticulum stress, adiponectin, lipid-peroxidation, signaling pathways, metabolic syndrome, miRNA and heme oxygenase-1." (PMID 40441190, 2025). "In our study, we found that OLE treatment during differentiation led to an overexpression of heme oxygenase 1 (HO-1), an inducible enzyme known for its protective and antioxidant effect in vascular disease and in the metabolic syndrome." (PMID 27303302, 2016). "Emerging literature supports the idea of a Janus-faced role for HMOX1 in regulating ferroptosis, with evidence that it not only can protect from oxidative cell death, but also induce ferroptosis in specific contexts, including endotoxin-induced inflammation, sterile injury, and metabolic syndrome." (PMID 38585264, 2024). "The induction of the antioxidant enzyme Heme oxygenase-1 (HO-1) or the upregulation of its nuclear co-activator, PGC1 α, confers advantageous effects on metabolic syndrome." (PMID 36231029, 2022). "Activated Nrf2 can induce its downstream target genes heme oxygenase 1 (HO-1) and NAD(P)H dehydrogenase (quinone 1) (NQO1), which have antioxidant and anti-inflammatory functions, and which regulate metabolic syndrome." (PMID 34684455, 2021).